ATAD2 (ATPase family AAA domain containing 2)
Diseases named in the same sentence as ATAD2 in open-access papers (continued):
Sharing a sentence is not in itself a finding about the gene and the disease.
tumor (continued). "Univariate analysis indicated that ATAD2 expression status, tumor size, metastasis, serum AFP, and TNM stage unfavorably influenced OS." (PMID 32462022, 2020). "Tumor size and metastatic status seemed to have little effect on the prognostic value of ATAD2 expression status on OS." (PMID 32462022, 2020). "Studies have shown that ATAD2 is involved in the regulation of chromatin dynamics, transcription and apoptosis, which can facilitate the proliferation of tumor cells and inhibit their differentiation." (PMID 32669963, 2020). "ATPase family AAA domain-containing protein 2 (ATAD2) is highly expressed in a variety of malignancies and can promote the proliferation of tumor cells and inhibit their differentiation." (PMID 32669963, 2020). "The immunoreactivity of ATAD2 is characterized by nuclear and cytoplasmic expression in tumor cells, especially in the nucleus, but rarely in the oral mucosa." (PMID 32669963, 2020). "High ATAD2 expression was positively related to tumor size, metastasis, serum AFP concentration, and TNM stage in our study." (PMID 32462022, 2020). "Examination of the correlation between ATAD2 relative expression and clinicopathological features showed that ATAD2 upregulation correlated with larger tumor size (P = 0.014)." (PMID 29515109, 2018). "Our results validate that ATAD2 is an important negative regulator of apoptosis, and that neutralizing its activity has promising anti-tumor effects in HCC cells." (PMID 26497681, 2015). "Our study shows that in HCC, ATAD2 is a feasible therapeutic target, due to its clinical association with aggressive HCC phenotypes, and its biological functions in promoting tumor cell growth and invasion." (PMID 26497681, 2015). "After four weeks, the tumor volumes of ATAD2-shRNA groups (in both HepG2 and Hep3B xenografts) were significantly smaller than that of control groups (p < 0.05)." (PMID 26497681, 2015). "The suppression of ATAD2 expression elicited anti-tumor functions, including inhibition of HCC cell proliferation, migration, and invasion, while inducing apoptosis in vitro." (PMID 26497681, 2015). "Using tissue samples (51 HCC and 27 non-tumor liver) from the same patient cohort, we validated over-expression of ATAD2 transcript in HCC using TaqMan real-time semi-quantitative PCR (p < 0.0001)." (PMID 26497681, 2015). "Previous studies had demonstrated that overexpression of ATAD2 at the transcriptional level via miR-372 regulation promotes tumor malignancy and consequently results in poor outcome in liver adenocarcinoma patients." (PMID 26697062, 2015). "Univariate Cox regression analyses showed that ATAD2 expression, tumor size, serum CEA, liver metastasis, and clinical stage were significantly associated with overall survival (OS)." (PMID 26697062, 2015). "Consistently, ATAD2 suppression in subcutaneous HCC xenografts delayed tumor cell growth, accompanied by apoptosis induction." (PMID 26497681, 2015). "Immunohistochemical (IHC) staining of a small subset of this patient cohort (n = 9; HCC and paired non-tumor liver) further validated the over-expression of ATAD2 protein in five out of these nine HCC patients (55.6%)." (PMID 26497681, 2015). "The multivariate Cox regression analysis confirmed ATAD2 expression, tumor size, and clinical stage as independent predictors of the OS in CRC patients." (PMID 26697062, 2015). "From the Human Tumor Metastasis RT-PCR array with ATAD2 siRNA-treated cells, we identified APC, ITGB3, FXYD5, ITGA7 and CTNNA1 (α-catenin), which are related to cell adhesion; among these, the expression of APC and CTNNA1 changed by at least 3-fold." (PMID 24552534, 2014). "The ATAD2 protein appeared to be expressed in both the nucleus and the cytoplasm of tumor cells, with stronger expression in the nucleus." (PMID 24552534, 2014).
tumor (continued). "Further correlation analyses indicated that the high expression of ATAD2 in the HCC tissues was positively correlated with tumor metastasis." (PMID 24552534, 2014). "IHC showed that ATAD2 expression in the HCC tissues was significantly higher than in adjacent non-tumor tissues." (PMID 24552534, 2014). "Similarly, intracranial tumor formation experiments showed a notable reduction in tumor volume after ATAD2 knockdown." (PMID 41158756, 2026). "Numerous studies have highlighted the involvement of ATAD2 in various tumor metabolic processes." (PMID 41158756, 2026). "In early-stage Caco-2 cell tumors, ATAD2 was ubiquitously expressed in most tumor cells." (PMID 40050746, 2025). "Moreover, subcutaneous tumor analysis revealed that Ki67 staining abundance was significantly enhanced following ATAD2 overexpression." (PMID 37233956, 2023). "Moreover, ATAD2 has also been identified as a coactivator of ERα, AR, E2Fs, and c-Myc for the promotion of tumor progression." (PMID 36632213, 2023). "As expected, the ATAD2 protein level also increased in ccRCC tumor tissues." (PMID 37233956, 2023). "A positive correlation was observed between ATAD2 and tumor purity (cor = 0.032, P = 5.89e − 01)." (PMID 36479043, 2022). "Furthermore, in vitro molecular biology and in vivo functional experiments were employed to ascertain the effect of ATAD2 expression on tumor angiogenesis and tumor growth." (PMID 36479043, 2022). "Moreover, a significant correlation between the mean ATAD2 expression and the mean mRNA‐SI score across tested tumor types suggests that strongly de‐differentiated tumors overexpress ATAD2." (PMID 35049055, 2022). "The expression of MALAT1, miR-655-3p, and ATAD2 in tumor tissue of nude mice were also analyzed." (PMID 34222668, 2021). "ATAD2 is often overexpressed in many human tumors, and its aberrant expression has been correlated with high histologic grades, poor overall survival (OS), tumor metastasis, and recurrence." (PMID 32462022, 2020). "ATAD2 has also been identified as a coactivator of hormone-induced nuclear receptors (oestrogen receptor alpha (ERα) and androgen receptor (AR)), E2Fs, and c-myc for the promotion of tumor progression." (PMID 32462022, 2020). "Previous studies have suggested that silencing ATAD2 may inhibit malignant tumor biological phenotypes, such as invasion, metastasis, and proliferation, consistent with our previous results regarding HCC." (PMID 32462022, 2020). "The discovery of the ATAD2 gene is a new breakthrough in the field of tumor molecular biology." (PMID 32669963, 2020). "Furthermore, elevated ATAD2 protein levels are related to tumor stage, histological grade, and lymph node metastasis." (PMID 29515109, 2018). "The general function of ATAD2 in DNA replication proposed here may explain why ATAD2 is highly expressed in many unrelated tumor types." (PMID 27612420, 2016). "Thus, the inhibitions of ATAD2 expression or of its interactions with MKK3/6 are potential therapeutic strategies by which apoptosis can be stimulated to achieve anti-tumor effects." (PMID 26497681, 2015). "In addition, a multivariate analysis demonstrated that ATAD2 status, the tumor size, metastasis and the AFP status were significant prognostic factors for HCC patients." (PMID 24552534, 2014). "ATAD2 was overexpressed in 83 of 129 tumor samples (83/129, 64.3%) according to IHC." (PMID 24552534, 2014). "For instance, ATAD2 has been implicated in modulating the Rb/E2F axis that controls cell cycle progression, as well as oncogenic pathways such as PI3K/AKT and MAPK signaling, highlighting its potential to influence several regulatory networks that adapt during tumor progression." (PMID 41154392, 2025). "Notably, Caco-2 cells exhibited high ATAD2 expression under standard culture conditions, showing that Caco-2 cells could maintain high ATAD2 expression in both in vitro culture and in vivo tumor environments." (PMID 40050746, 2025).
tumor (continued). "Thus, ATAD2 has been shown to be an important driver of tumor growth and progression." (PMID 37479754, 2023). "Furthermore, in vivo animal experiments established that ATAD2 promoted tumor growth." (PMID 36479043, 2022). "However, ATAD2 overexpression rescued the decreased tumor growth seen after miR-302 overexpression." (PMID 36139505, 2022). "In addition, several intracellular mediators that regulate ATAD2, such as long non-coding RNAs and microRNAs, and drugs targeting these mediators may also be a new option for tumor therapy." (PMID 36008934, 2022). "However, restoration of ATAD2 reversed the inhibitory effect of miR-302 on tumor growth." (PMID 36139505, 2022). "Interestingly, ATAD2 expression was strongly restricted to the proliferating area of each tumor, as marked by Ki67 and Topoisomerase 2A (TOP2A) staining, suggesting that ATAD2 might be implicated in cell proliferation and cell cycle progression." (PMID 27612420, 2016). "NAT10 remodeled the ac4C modification of the mRNAs of the oncogenic genes ATAD2, SOX4, and SNX5, which have been confirmed to play important roles in tumor metastasis and angiogenesis." (PMID 40301349, 2025). "Aberrant activation of the Hedgehog (HH) signaling pathway contributes to tumor development, and in HCC, ATAD2 depletion reduces the expression of HH pathway proteins." (PMID 41154392, 2025). "To elucidate the role of TGF-β signaling in ATAD2-mediated tumor metastasis, we blocked TGF-β signaling in ATAD2-overexpressed KYSE510 and KYSE30 cells using TGF-β1 receptor inhibitors." (PMID 33757572, 2021). "Regarding these, lncRNA NEAT1_2 overexpression, sponging mir-106b-5p and enhancing ATAD2 protein expression, plays an important role in TNM stage and tumor size." (PMID 35186709, 2021). "Silencing ATAD2 significantly suppressed ESCC cell migration and invasion in vitro, and inhibited tumor growth and lung metastasis in vivo." (PMID 33757572, 2021). "DEmRNAs, including ATAD2, KIF23, MCM4, CCNB1, and CCNE1, are highly expressed in LUAD than in corresponding non-tumor tissues." (PMID 33042838, 2020). "Herein, our evidence suggests that low ATAD2 expression is related to reduce EMT in OSCC cells and further affects tumor metastasis." (PMID 32669963, 2020). "Differential gene expression analysis revealed 3155 DEGs (differentially expressed genes), among which six AAA ATPase genes (TRIP13, CHTF18, RFC4, ATAD2, FIGNL2, ATAD5) were significantly overexpressed in tumor samples compared to levels in normal samples." (PMID 31533816, 2019). "Specifically, we showed that over-expression of ATAD2 correlated significantly with high AFP levels, advance tumor stages, and vascular invasion." (PMID 26497681, 2015). "We demonstrated that ATAD2 was over-expressed in HCC patients, where high ATAD2 levels were significantly correlated with aggressive phenotypes such as high AFP levels, advanced tumor stages, and vascular invasion." (PMID 26497681, 2015). "The direct interactions of ATAD2 with MKK3/6 prevent p38 activation, and contribute to tumor progression." (PMID 26497681, 2015). "In addition, ATAD2 silencing inhibits EMT through upregulation of E-cadherin and downregulation of vimentin in CRC cells, thereby preventing tumor invasion and migration." (PMID 36632213, 2023). "Finally, the TIMER, Tumor Immune System Interaction and Drug Bank (TISIDB), and GEPIA databases were used to analyze the relationship between ATAD2 and immune infiltration." (PMID 36479043, 2022). "Quantification of staining intensity according to ImageJ software demonstrated that 14.0% of the area in the tumor stage IIA sample, 16.8% in tumor stage IIB, 29.8% in tumor stage IIIA, 33.0% in tumor stage IIIB, 44.6% in tumor stage IIIC, compared to 3.4% in normal tissues, was ATAD2 positive." (PMID 36139505, 2022). "In the tumor size and metastasis subgroup, patients with high ATAD2 levels had a poorer prognosis than those with low ATAD2 levels, regardless of tumor size or metastasis status." (PMID 32462022, 2020).
tumor (continued). "We found that ATAD2 was significantly upregulated in tumor tissues compared with its expression in adjacent non-cancerous tissues." (PMID 29515109, 2018). "The suppression of ATAD2 expression elicited anti-tumor functions, including inhibition of HCC cell proliferation, migration, invasion and ATAD2 suppression in subcutaneous HCC xenografts delayed tumor cell growth, accompanied by apoptosis induction." (PMID 28449718, 2017). "Although the majority of CTA peptides were only found to be unique in one patient, we identified multiple peptides derived from CTA-associated genes that were present in a substantial portion of patients independent of the tumor entity (e.g. ATAD2, SPAG9, ODF2, and KIAA0100)." (PMID 37532709, 2023). "Because c-Myc enhances glycolysis without hypoxia and alters tumor cell metabolism, we speculated that ATAD2 cooperates with c-Myc to promote glycolysis in ccRCC cells." (PMID 37233956, 2023). "However, neither pathology grade (p > 0.05), nor tumor size (p > 0.05) was related to the expression of ATAD2." (PMID 32669963, 2020). "As in AFP and GPC3 detection, ATAD2 may become a prospective molecular biomarker, allowing for the early diagnosis and treatment of HCC patients, thereby avoiding the adverse effects of tumor progression." (PMID 32462022, 2020). "We extracted ATAD2 transcript expression data from our earlier gene expression profiling study of HCC patients, and observed significant over-expression of ATAD2 transcript in HCC tissues compared to matched adjacent non-tumor liver in 75 HCC patients (p < 0.05)." (PMID 26497681, 2015). "Only for five genes, namely KAT2A, SMARCA4, BAZ1A, ATAD2 and TRIM28, we observed consistently higher levels and for two genes—KAT2B and SMARCA2—lower levels, respectively, regardless of the tumor type." (PMID 35049055, 2022).
adenocarcinoma (2 papers, 2016 to 2024). A common cancer characterized by the presence of malignant glandular cells. "The present results also exhibit that among the amplified genes, the following eight genes involved in the cell cycle were found to be amplified in more than 5% of HGSO adenocarcinoma patients: ATAD2, ASF1B, CCNE1, CDC20, CDCA8, RECQL4, RNASEH2A, and SMC4." (PMID 39199556, 2024).
cardiovascular disease (1 paper, 2025). "The role of ATAD2 and TCF19 in cardiovascular disease was so far unknown." (PMID 40962957, 2025).
infection (1 paper, 2021). The state of being infected such as from the introduction of a foreign agent such as serum, vaccine, antigenic substance or organism. "ATAD2 has a ATP-binding site and ATPase activity, regulating the assembly of protein complexes, as CREB-binding promoter region or regulating histone hyperacetylation, suggesting the ATAD2/miR-548d can alter gene transcription during infection." (PMID 34178725, 2021).
ATAD2 also shares sentences with these, for which no sentence is quoted: Cirrhosis (2 papers); astrocytoma (1); Fanconi anemia (1); mammary adenocarcinomas (1); metastatic colorectal cancer (1); metastatic disease (1); myocardial infarction (1); non-small cell lung carcinoma (1); oligodendroglioma (1); renal cell carcinoma (1); squamous cell lung carcinoma (1); stomach cancer (1); uterine cancer (1); uterine corpus endometrial carcinoma (1).